JAK2 (Janus kinase 2)
Diseases named in the same sentence as JAK2 in open-access papers (continued):
Sharing a sentence is not in itself a finding about the gene and the disease.
glioma (continued). "Moreover, IL-6 also increased cell proliferation, migration and invasion by activating JAK2/STAT3 signaling pathway in human glioma cells." (PMID 34165442, 2021). "NC can inhibit the EMT process and glioma stem cell characteristics of glioma cells via modulation of JAK2/STAT3 signaling, suggesting that NC may be a potential anti‐glioma drug." (PMID 33788424, 2021). "Considering that the JAK2/STAT3 signaling pathway is overactivated in glioma cells, we speculate that fraxetin may play an antiglioma effect by inhibiting JAK2/STAT3 signaling." (PMID 33959183, 2021). "These experimental results demonstrated that JAK2/STAT3 signaling was involved in the EMT process of glioma cells and suggested that the inhibitory effect of NC on glioma EMT may be achieved via the JAK2/STAT3 pathway." (PMID 33788424, 2021). "Based on above results, we speculated that ELK3 overexpression might promote the malignant growth, proliferation, and migration of gliomas through regulating expression of JAK2 and STAT3, especially STAT3." (PMID 34976781, 2021). "Our current results showed that AP-2α could downregulate IL6 expression and block the Jak2/STAT3 signaling pathway in glioma." (PMID 31534499, 2019). "Mechanistically, BMX bypasses the suppressor of cytokine signaling 3 (SOCS3)-mediated inhibition of JAK2, whereas targeting of the BMX dampens the JAK2-mediated STAT3 activation, underlying a new molecular basis in which to specifically eliminate the glioma stem cells." (PMID 31130822, 2019). "Furthermore, we for the first time found that IL-10 stimulated the JAK2/STAT3 pathway in glioma cell lines U271 and U87 through interaction with JAK2 in a protein-protein interaction fashions." (PMID 27765933, 2016). "Further, IL-10 was found to be able to interact with JAK2 in glioma cells." (PMID 27765933, 2016). "Given the high occurrence of this mutation and the selectivity of Jak2 inhibitors for EGFRvIII-positive glioma cells, stratifying patients by EGFR mutation status may be an important factor in assigning Jak2 inhibitor therapy." (PMID 25162558, 2014). "Others have targeted the JAK2/STAT3 pathway in glioma stem-like cells (GSCs)." (PMID 24518612, 2014). "NIBAN2 may promote glioma growth by activating the JAK2/STAT3 signaling pathway." (PMID 40944417, 2025). "Besides, our results further revealed that the upregulation of ARSD, which promoted glioma cell proliferation, migration and invasion, could be effectively inhibited by the JAK2/STAT3 pathway inhibitor AG490." (PMID 37766864, 2023). "Moreover, the inhibitory effect of NC in glioma cells may be achieved through altered JAK2/STAT3 pathway activity." (PMID 33788424, 2021). "Therefore, the JAK2/STAT3 signaling may be involved in fraxetin-mediated antitumor effects on glioma." (PMID 33959183, 2021). "In addition, we evaluated the activity of JAK2/STAT3 signaling in glioma." (PMID 33959183, 2021). "Furthermore, fraxetin was able to effectively inhibit the JAK2/STAT3 signaling in glioma." (PMID 33959183, 2021). "The expression of β-catenin, p-JAK-2, and p-STAT3 in normal human brain tissue was much lower than that in glioma tissues." (PMID 38397980, 2024). "Overexpression of SRPK1 activates the Wnt/β-catenin and JAK-2/STAT-3 signaling pathways, promoting the proliferation, migration, and invasion of gliomas." (PMID 38397980, 2024). "As STAT3 is a transcription factor that promotes cell survival and proliferation when activated, inhibiting JAK2, and subsequently STAT3 allows resveratrol to exert growth-inhibitory effects on glioma cells." (PMID 39769099, 2024).
glioma (continued). "Cell experiment showed that modulation of the JAK2/STAT3 pathway by CTR9 was found to promote proliferation, migration, and invasion of glioma cells." (PMID 37766864, 2023). "Our study found that ARSD can promote glioma development by regulating immune microenvironment and JAK2/STAT3 signaling pathway, which provided a potential therapy target for glioma treatment." (PMID 37766864, 2023). "When the murine glioma cell lines were treated with curcumin, it led to the dephosphorylation of JAK1 and JAK2 in a dose-dependent manner." (PMID 37998723, 2023). "Combination treatment with the chemotherapeutic agent temozolomide and an inhibitor of ROS1, JAK2, or a downstream target of STAT3, demonstrated antitumor effects against KLC1-ROS1 fusion-expressing glioma cells." (PMID 38201436, 2023). "One of our findings shows that TRPM7 activates JAK2/STAT3 signaling pathways and leads to increased glioma cell proliferation and migration/invasion." (PMID 37642779, 2023). "In glioma cells, the phosphorylation of STAT3 and JAK2 is obviously increased, which contributes to the proliferation-promoting and the apoptosis-inhibiting in glioma cells." (PMID 37716993, 2023). "We will delve into the current literature regarding the role of autophagy in glioma pathogenesis by exploring the major pathways of JAK2/STAT3 and PI3K/AKT/mTOR and summarizing the current therapeutic interventions and strategies for glioma treatment." (PMID 37998723, 2023). "In glioma, NIC promotes the overexpression of ALK4, which significantly downregulates the phosphorylation of JAK 2 and STAT3, thus inhibiting the migration and invasion ability of glioma cells." (PMID 36555754, 2022). "In glioma, GOLPH3 was found to facilitates the interaction of JAK2 and STAT3, leading to activation of the STAT3 pathway." (PMID 35372504, 2022). "Phosphorylation of JAK2 activates STAT3 expression and induces abnormal proliferation of glioma cells, which finally leads to further deterioration of the disease and endangers life." (PMID 36065261, 2022). "By inhibiting phosphorylation of JAK2 and STAT3, which are highly activated in many malignant cells, including glioma cells, miR-33a inhibits the growth, invasion, and EMT of tumor cells." (PMID 36061185, 2022). "The expression of IL-6 often remains at a high level in gliomas, especially GBM, which results in the overactivation of the JAK2/STAT3 pathway and induces stronger EMT." (PMID 36338770, 2022). "The overexpression of EGFR will excessively activate EGFR-dependent signal pathways including PI3K/Akt, JAK2/STAT3, and Ras/MAPK in the course of EMT in gliomas." (PMID 36338770, 2022). "In summary, we found that exosomal miR-3591-3p can facilitate macrophage polarization toward the M2 phenotype by targeting CBLB to activate the JAK2/PI3K/Akt/mTOR and STAT3 pathways, which in turn promotes glioma progression." (PMID 36085418, 2022). "Mechanistically, miR-3591-3p can directly target CBLB and MAPK1 in macrophages and glioma cells, respectively, and further activate the JAK2/PI3K/AKT/mTOR, JAK2/STAT3, and MAPK signaling pathways." (PMID 36085418, 2022). "A recent study indicated that the binding of T cells to glioma cells calls for the IFNγR signaling pathway (IFNGR1, JAK1 and JAK2) in which IFNGR1 was found necessary for this kind of cell-cell adhesion." (PMID 36309750, 2022). "HOXB5 was overexpressed in glioma and transcriptionally regulated IL6 expression and promoted the proliferation of GSCs via JAK2/STAT3 signaling." (PMID 33858489, 2021). "The experimental results exhibited that NC treatment inhibited the expression of JAK2, p‐JAK2, STAT3, and p‐STAT3 in glioma cells, and these inhibitory effects increased with increasing NC concentration." (PMID 33788424, 2021). "To determine the mechanism by which STAT3 was inhibited by the combination of sorafenib and TMZ, we assessed JAK2, an upstream molecule that regulates STAT3 in glioma cells." (PMID 34277607, 2021).
glioma (continued). "In summary, our results show that fraxetin inhibits proliferation, invasion, and migration of glioma by inhibiting JAK2/STAT3 signaling and inducing apoptosis of glioma cells." (PMID 33959183, 2021). "The results showed that NC inhibited the glioma EMT process and the properties of glioma stem‐like cells by modulating the JAK2/STAT3 signaling pathway, suggesting the potential of NC to serve as an effective anti‐glioma drug." (PMID 33788424, 2021). "AP-2α was found to suppress classically activated (M1) macrophages producing the cytokine IL-6 and Jak2/STAT3 activation and subsequently decrease PD-L1 expression in glioma cells." (PMID 31534499, 2019). "WP1193 is a small molecule inhibitor of JAK2/STAT3, which promotes in vivo glioma inhibition in a dose-dependent manner and is partially associated with G1 arrest in GSCs." (PMID 24518612, 2014). "Moreover, SRPK1 directly regulates the Wnt/β-catenin and JAK2/STAT-3 signaling pathways, thus promoting glioma development." (PMID 41141389, 2026). "This characteristic makes USP38 a promising candidate for targeted cancer therapy, as the USP38/JAK2/STAT3 signaling axis regulation may be specific to certain malignancies, such as glioma." (PMID 40936898, 2025). "Therefore, resveratrol’s ability to inhibit JAK2 and STAT3 signaling pathways positions it as a potential therapeutic agent in gliomas, leading to reduced tumor growth and increased apoptosis." (PMID 39769099, 2024). "Based on these findings, we speculate that the activation of the Wnt/β-catenin and JAK-2/STAT-3 signaling pathways by SRPK1 promotes the proliferation, migration, and invasion of gliomas." (PMID 38397980, 2024). "The JAK2/STAT3 pathway is important in many cancers, especially gliomas." (PMID 38661644, 2024). "Blocking of the IL-6-mediated JAK2/STAT3 pathway could substantially suppress the proliferation and promote the apoptosis of glioma cells." (PMID 38715108, 2024). "JAK2/STAT3 and Notch1 signaling activation.Glioma stem marker expression." (PMID 37762011, 2023). "In addition, the activation of JAK2/STAT3 pathway regulates malignant behaviors of glioma cells, including the proliferation and invasion of glioma cells." (PMID 36814203, 2023). "In glioma, TFAP2A disturbs the expression of stemness-related genes, such as NANOG, SOX2 and CD133, via both directly binding the regulation region of NANOG and indirectly interfering with the IL6/JAK2/STAT3 signaling pathway." (PMID 37291585, 2023). "MiR-33a may exert oncogenic effects by regulating JAK2/STAT3, cAMP/PKA, and NOTCH signaling pathways in gliomas." (PMID 36061185, 2022). "Results showed that expressions of IFNGR1 and JAK1 were significantly higher compared to the other three glioma cell types, but expression of JAK2 was not obviously different." (PMID 36309750, 2022). "The correlation between the JAK2/STAT3 pathway and glioma is extremely high." (PMID 36065261, 2022). "In addition, some studies have pointed out that the JAK2/STAT3 pathway can act as an upstream immune signal to regulate the PI3K/AKT pathway and affect the therapeutic effect of glioma." (PMID 36065261, 2022). "Inhibition of JAK2 activity with AG490, WP1066, sorafenib, and WP1193 downregulated STAT3 activity, inhibited proliferation, migratory/ invasive behavior, and focal adhesion kinase signaling of glioma cell lines, and resulted in apoptosis." (PMID 33960104, 2022). "As an effective JAK2/STAT3 inhibitor, NC represents a promising agent for the treatment of glioma." (PMID 33788424, 2021). "STAT3, a downstream molecule of JAK2, is a member of the family of the signal transducer and activator of transcription (STAT), which is constitutively activated in most cancers, including glioma." (PMID 33959183, 2021). "Taken together, these results indicate that NC inhibits the EMT process and glioma stem‐like properties via JAK2/STAT3 signaling pathway, suggesting that NC may be a potential anti‐glioma drug." (PMID 33788424, 2021).
glioma (continued). "Moreover, miR-26a alleviated the inhibitory effect of AP-2α and the miR-26a inhibitor on glioma cells by upregulating the expression of Nanog/Sox2 and the IL6/Jak2/STAT3 signaling pathway." (PMID 31534499, 2019). "Having found that IL-10 secreted from M2 macrophages was dependent on the JAK2/STAT3 signaling pathway and that co-culture with glioma cells was able to activate the JAK2/STAT3 signaling pathway in M2 macrophages, we've next tried to understand how IL-10 was dependent on JAK2/STAT3 pathway." (PMID 27765933, 2016). "However, there are currently no studies indicating a role for CARD11 and JAK2 in glioma progression." (PMID 40685627, 2025). "To clarify the role of JAK2/STAT3 signaling in glioma EMT and determine whether NC modulates JAK2/STAT3 signaling as a mechanism for inhibiting EMT in glioma cells, we used WP1066 to inhibit JAK2/STAT3 activity in U87 and LN18 glioma cells during exposure to TGF‐β1 for the induction of EMT." (PMID 33788424, 2021). "However, the action of the JAK2/STAT3 signaling pathway in glioma cell EMT and glioma stem cells has not been fully elucidated." (PMID 33788424, 2021). "Taking together, we for the first time found that IL-10 from M2 macrophage promoted proliferation of glioma through interaction with JAK2; thereby activating the JAK2/STAT3 pathway, indicative of IL-10 could be used as a therapeutic target in the curing of glioma." (PMID 27765933, 2016). "In glioma cells, the up-regulation of MMP-13 by leptin was mediated through p38 MAP kinase and NF-κB pathway, while in pancreatic cancer cells, we found that the expression of MMP-13 was regulated through JAK2/STAT3 signaling pathway in response to leptin stimulation." (PMID 25948792, 2015). "Therefore, a comprehensive understanding of the abnormal expression of members of the JAK2/STAT3 signaling pathway and the effects on the classic EMT process and cancer stem cells provide new ideas for the development of methods to effectively inhibit the malignant progression of glioma." (PMID 33788424, 2021). "To investigate whether NC inhibits the expression of stem cell‐related markers through the modulation of JAK2/STAT3 signaling, we used WP1066 to inhibit JAK2/STAT3 signaling and further studied the effect of JAK2/STAT3 activity on the expression of stem cell markers in glioma cells." (PMID 33788424, 2021).
acute myeloid leukemia (79 papers, 2007 to 2026). Acute myeloid leukemia (AML) is a group of neoplasms arising from precursor cells committed to the myeloid cell-line differentiation. "Patients with acute lymphoblastic leukemia, acute myeloid leukemia, and acute mega-karyoblastic leukemia also showed JAK2 mutations." (PMID 40109858, 2025). "Our proteomic studies revealed RAB27B upregulation in CBL- or JAK2-mutated myeloid malignancies, and its expression correlated with poor prognosis in acute myeloid leukemias (AMLs)." (PMID 37317963, 2023). "In one study on 132 patients with MDS, a JAK2 mutation was associated with a lower rate of progression to acute myeloid leukemia, a better overall survival, and possibly a favorable prognosis." (PMID 36810551, 2023). "In patients with acute myeloid leukemia, IL-27Rα has been linked to transformation through its ability to dimerize and to constitutively activate a mutant form of Jak2." (PMID 24130734, 2013). "In one study, 35 unique JAK2 variants were reported across different functional domains and specific JAK2 variants detected in MPNs may predict evolution to acute myeloid leukemia." (PMID 36810551, 2023). "Moreover, in JAK2-mutated MPNs two routes of leukemic transformation have been demonstrated by analyzing 16 patients with a JAK2-mutant or JAK2 wild-type acute myeloid leukemia after a JAK2-mutated MPN." (PMID 32674283, 2020). "JAK2 mutation is believed to have prognostic impact in acute myeloid leukemia." (PMID 31874600, 2019). "RAB27B overexpression in myeloid malignancies with CBL or JAK2 mutations correlates with poor acute myeloid leukemia (AML) prognosis." (PMID 40977744, 2025). "In murine acute myelogenous leukemia models, the Jak2-R1063H cooperated with a driver oncogene in promoting leukemogenesis." (PMID 40841769, 2025). "In a similar manner, pacritinib has been shown to have activity in acute myeloid leukemia cells with drug resistance to FLT3 therapy because of its combined JAK2/FLT3 activity." (PMID 38374336, 2024). "A small molecule inhibitor of JOSD1 was shown to induce cell death of JAK2-V617F-positive primary acute myeloid leukemia (AML) cells." (PMID 37892185, 2023). "Another GOF position, JAK1 Val658, is mutated in acute myeloid leukemia (AML); this residue is structurally analogous to JAK2 Val617, which is commonly mutated in polycythemia vera." (PMID 36669486, 2023). "On the other hand, the JAK2 V617F mutation may—though rarely—occur also in de novo acute myeloid leukemia (AML)." (PMID 34771693, 2021). "JAK2 inhibitors like baricitinib, gandotinib and lestaurtinib are being tested in clinical trials for a variety of diseases including acute myeloid leukemia." (PMID 31116490, 2019). "Infrequent occurrence of this unique JAK2 mutation has been reported recently in chronic myeloid leukemia (CML), acute myelocytic leukemia, and acute lymphoblastic leukemia." (PMID 31870101, 2019). "Cephalon’s lestaurtinib is in phase III trials for treatment of acute myeloid leukemia and is an inhibitor of janus kinase 2 (JAK2), FLT3, and tropomyosin receptor kinase (Trk) family kinases." (PMID 25013742, 2013). "In acute myeloid leukemia (AML), YBX1 serves as a disease-sustaining mediator of jak2-mutated myeloproliferative neoplasms, enhancing the translational capacity of oncogenic transcripts (including MYC) by recruiting polysome chains, thereby driving the survival and proliferation of AML cells." (PMID 40799245, 2025). "Recent data demonstrated that mutations of these two genes have opposite consequences on PARPi sensitivity in acute myeloid leukaemia (AML) cells expressing oncogenic tyrosine kinases (e.g., mutated FLT3 or JAK2), which are characterised by high endogenous levels of DNA DSB." (PMID 36612003, 2022). "Furthermore, the median CALR allele burden remained steady over time; interestingly, differently from JAK2-positive cases, acute myeloid leukemias (AML) evolving from CALR-mutant MPNs commonly maintained their mutational profile." (PMID 31106152, 2019).